LILRP1 (leukocyte immunoglobulin-like receptor pseudogene 1)
Synonyms: ILT9; CD85l; LILRA6P
Gene: Transcribed unprocessed pseudogene on chromosome 19 (54,696,604 to 54,700,905, forward strand). Ensembl gene ENSG00000186152.
Diseases named in the same sentence as LILRP1 in open-access papers:
LILRP1 is named in the same sentence as 2 diseases in open-access papers, as found by Europe PMC text mining. Sharing a sentence is not in itself a finding about the gene and the disease. The quoted sentences say what the papers report.
head and neck squamous cell carcinoma (1 paper, 2021). A squamous cell carcinoma that arises from any of the following anatomic sites: lip and oral cavity, nasal cavity, paranasal sinuses, pharynx, larynx, and salivary glands. "Another group of five pseudogenes in head and neck squamous cell carcinoma (HNSCC), LILRP1, RP6-191P20.5, RPL29P19, TAS2R2P, and ZBTB45P1, can be used as prognostic or predictive markers." (PMID 34947885, 2021).
LILRP1 also shares sentences with these, for which no sentence is quoted: tumor (1 paper).